IGFBP5 (insulin like growth factor binding protein 5)
Description:
Multifunctional protein that plays a critical role in regulating the availability of IGFs to their receptors and thereby regulates IGF-mediated cellular processes including proliferation, differentiation, and apoptosis in a cell-type specific manner. Increases the cell proliferation of osteoblasts, intestinal smooth muscle cells and neuroblastoma cells. Enhances adhesion and survival of epithelial cells but decreases adhesion of mesenchymal cells (By similarity). Once secreted, acts as a major mediator of mTORC1-dependent feedback inhibition of IGF1 signaling (By similarity). Also plays a role in the induction of extracellular matrix (ECM) production and deposition independently of its nuclear translocation and binding to IGFs. Acts itself as a growth factor that can act independently of IGFs to regulate bone formation. Acts as a ligand for the ROR1 receptor which triggers formation of ROR1/HER2 heterodimer to enhance CREB oncogenic signaling.
Synonyms: IBP5
Tractability: Small molecule: it belongs to a druggable protein family. Antibody: UniProt places it where antibodies can reach, with high confidence; its Gene Ontology location is reachable by antibodies, with high confidence; UniProt predicts a signal peptide or a membrane-spanning region. PROTAC: its protein half-life has been measured; a small molecule that binds it is known.
Target class: Secreted protein
Gene: Protein-coding gene on chromosome 2 (216,672,105 to 216,695,549, reverse strand). Ensembl gene ENSG00000115461.
Subcellular location: Secreted; Cytoplasm; Nucleus
Subcellular location (Human Protein Atlas): Vesicles; Predicted to be secreted
Pathways (Reactome):
Metabolism of proteins: Post-translational protein phosphorylation; Regulation of Insulin-like Growth Factor (IGF) transport and uptake by Insulin-like Growth Factor Binding Proteins (IGFBPs)
Gene Ontology:
Molecular function: insulin-like growth factor I binding; protein binding; receptor ligand activity; fibronectin binding; insulin-like growth factor II binding; insulin-like growth factor binding
Biological process: cell population proliferation; cellular response to cAMP; negative regulation of cell migration; negative regulation of insulin-like growth factor receptor signaling pathway; negative regulation of smooth muscle cell migration; negative regulation of smooth muscle cell proliferation; negative regulation of translation; positive regulation of vascular associated smooth muscle cell migration; positive regulation of vascular associated smooth muscle cell proliferation; regulation of insulin-like growth factor receptor signaling pathway; response to growth hormone; signal transduction; female pregnancy; intracellular signal transduction; lung alveolus development; negative regulation of growth; negative regulation of muscle tissue development; negative regulation of skeletal muscle hypertrophy; osteoblast differentiation
Cellular component: cytoplasm; extracellular region; insulin-like growth factor ternary complex; nucleus; endoplasmic reticulum lumen; insulin-like growth factor binding protein complex; non-collagenous component of interstitial matrix
Genetic constraint (gnomAD): Loss-of-function variants: 12 observed, 19.09 expected, observed/expected ratio (o/e) 0.63, 90% interval 0.4 to 1.02. The synonymous counts are far from expectation, so gnomAD's model fits this gene poorly and the ratio says little. Missense variants: 344 observed, 322.57 expected, observed/expected ratio (o/e) 1.07, 90% interval 0.98 to 1.17. Synonymous variants: 152 observed, 117.09 expected, observed/expected ratio (o/e) 1.3, 90% interval 1.14 to 1.49.
Homologues: Orthologues: chimpanzee IGFBP5 (99% identical), macaque IGFBP5 (99% identical), pig IGFBP5 (98% identical), dog IGFBP5 (97% identical), rabbit IGFBP5 (97% identical), mouse Igfbp5 (95% identical), rat Igfbp5 (94% identical), guinea pig IGFBP5 (92% identical), tropical clawed frog igfbp5 (64% identical), zebrafish igfbp5b (52% identical), zebrafish igfbp5a (46% identical). Paralogues in human: IGFBP3 (41% identical), IGFBP4 (32% identical), IGFBP2 (31% identical), IGFBP6 (31% identical), IGFBP1 (26% identical).
Diseases named in the same sentence as IGFBP5 in open-access papers:
IGFBP5 is named in the same sentence as 202 diseases in open-access papers, as found by Europe PMC text mining. Sharing a sentence is not in itself a finding about the gene and the disease. The quoted sentences say what the papers report.
breast cancer (85 papers, 2005 to 2026). A primary or metastatic malignant neoplasm involving the breast. "Clinical observations provided supporting evidence that IGFBP5 is associated with metastasis and the aggressive tumor phenotype in breast cancer." (PMID 37620794, 2023). "Contrary to these findings, IGFBP5 was found to inhibit growth of breast cancer cells in vitro and in vivo and IGFBP5 overexpression was associated with improved breast cancer patient outcome in another study." (PMID 37620794, 2023). "Overexpression of IGFBP5 also causes breast cancer cells to undergo apoptosis by increasing Bax and decreasing Bcl-2, thus regulating the ability to resist cell death." (PMID 36465383, 2022). "IGFBP5 displays allele-specific gene expression with g-allele downregulating the expression of IGFBP5 leading to the increased susceptibility to breast cancer." (PMID 35176995, 2022). "Single allelic enCNV of the 2q35 breast cancer risk loci repress expression of IGFBP5, which can be induced by oestrogen." (PMID 36465383, 2022). "This regulatory element increases cell-type-specific expression of the tumor suppressor gene IGFBP5 and, thereby, reduces risk of estrogen receptor-positive breast cancer (odds ratio = 0.77, 95% CI 0.74–0.81, p = 3.1 × 10−31)." (PMID 34146516, 2021). "We carry out functional annotation of credible variants at signals 2 and 3 and implicate the deletion variant (esv3594306) at signal 2 as causally associated with increased IGFBP5 expression and reduced breast cancer risk." (PMID 34146516, 2021). "Collectively, therefore, combining breast density, SNPs that reduce expression of IGFBP-5, pregnancy, and breastfeeding history holds the potential for the development of a predictive test for risk of breast cancer." (PMID 31046834, 2019). "For example, regulatory elements within the 2q35 breast cancer susceptibility locus loop onto both IGFBP5 and DIRC3 whilst copy number alterations encompassing an IGFBP5 enhancer on 2q35 modulate breast cancer risk." (PMID 31881017, 2019). "Further, small nucleotide polymorphisms leading to a reduction in IGFBP-5 expression have been identified by genome-wide association studies (GWAS) as a risk factor of developing breast cancer." (PMID 31046834, 2019). "The data suggested that the G-allele of rs4442975 refers to increased breast cancer susceptibility through reduced IGFBP5 expression." (PMID 26569312, 2015). "Overexpression of IGFBP5 has been found to be associated with poor outcomes of breast cancer patients." (PMID 26569312, 2015). "Insulin-like growth factor binding protein 5 (IGFBP5) has been shown to be associated with breast cancer metastasis in clinical marker studies." (PMID 19341485, 2009). "For instance, SNPs of IGFBP-5 is linked to increased risk of mammary tumors." (PMID 38395880, 2024). "In addition, genetic variations in IGFBP5 are associated with increased breast cancer risk in African-American patients." (PMID 36038558, 2022). "In addition, a recent GWAS have shown that low IGFBP-5 is linked to increased risk of breast cancer." (PMID 31046834, 2019). "Additionally, IGFBP-5 expression has also been implicated in controlling cellular adhesion, cell survival and cell migration in a breast cancer cell line." (PMID 26809067, 2016). "Further functional studies on DEGs and association with IGFBP5 may identify novel biomarkers for clinical applications in breast cancer." (PMID 26569312, 2015). "Using cDNA and tissue microarray technologies, we and others have found that IGFBP5 overexpression is associated with a poor prognosis and with metastasis in patients with breast cancer; however, the mechanism by which IGFBP5 promotes metastasis is unknown." (PMID 19341485, 2009). "Clinical observations show that IGFBP5 is associated with the metastatic tumor phenotype in breast cancer, thus IGFBP5 is a poor prognostic factor and may serve as a target for therapeutic development." (PMID 19341485, 2009).
breast cancer (continued). "Thus, a yet-to-be identified mechanism causing cytoplasmic localization of IGFBP5 operates in breast cancer tissues." (PMID 19341485, 2009). "In addition, IGFBP5 is critically associated with the proliferation and motility of cancer cells and others, such as breast cancer cells, glioblastoma, nucleus pulposus cells, dental pulp stem cells, periodontal ligament stem cells and Wharton's jelly of umbilical cord stem cells." (PMID 38886900, 2024). "Altogether, the link between rs16857609, breast cancer risk and IGFBP5 on one side, and the link between TC and IGFBP5 on the other suggests that a deregulation of IGFBP5 expression may also lead to the proliferation of thyroid cells and eventually to PTC development." (PMID 33747362, 2021). "Despite this, most studies are limited to the role of IGFBP5 in cancer, including breast cancer, colorectal cancer, and ovarian cancer." (PMID 40672360, 2025). "We propose that IGFBP5 mediates different biological process depending on the expression of PR, ER and Her2 receptors in breast cancer." (PMID 38896333, 2024). "IGFBP5 expression was markedly decreased upon the acquisition of resistance to tamoxifen in MCF-7 breast cancer cells, and its suppression was suggested to be a mechanism of cisplatin resistance in esophageal squamous cell carcinoma." (PMID 38999963, 2024). "Supporting our proposal, proteome analysis of canine mammary tumors demonstrate that IGFBP5 is highly expressed in the different stage of mammary tumors." (PMID 38896333, 2024). "Breast cancer cells release IGFBP5, IGF-I and insulin, and they regulate tumor progression in a paracrine and endocrine manner." (PMID 38896333, 2024). "This interaction between IGFBP5 and retinoid receptors has been examined in a breast cancer cell line." (PMID 38351010, 2024). "The nucleus IGFBP5 was detected in the breast cancer cell line (T47D), lung fibroblasts from idiopathic pulmonary fibrosis patients, and vascular smooth muscle cells." (PMID 36865533, 2023). "The mechanism by which GSK-J4 sensitises breast cancer cells to PI3K inhibitor involves silencing the IGFBP5 gene, which confers a growth advantage upon PI3K inhibitor-resistant breast cancer cells." (PMID 35915507, 2022). "A review that specifically explores the role of IGFBP5 in breast cancer details some of the studies that led to this work in greater depth." (PMID 36465383, 2022). "In breast cancer, Wnt was thought to be upstream of IGFBP5 to inhibit tumor growth, however in colon cancer Wnt is thought to be downstream of IGFBP5 to promote cell growth." (PMID 36465383, 2022). "A recent study evaluating mechanisms of PI3K inhibition in breast cancer revealed that the histone H3K27me3 demethylase KDM6B acted via IGFBP5 to confer resistance to PI3K inhibition and evasion of apoptosis." (PMID 36465383, 2022). "IGFBP5 also enhanced attachment of breast cancer cells to thrombospondin, and conferred resistance to ceramide induced apoptosis." (PMID 36465383, 2022). "Stromal cells induce IGFBP5 downregulation in ERα-positive breast cancer cells which results in desensitization to anti-estrogen therapies." (PMID 36465383, 2022). "For example, IGFBP5 directly interacts with α2β1 integrin on the surface of breast cancer cells to promote adhesion and inhibit migration." (PMID 35418167, 2022). "In the previous section, IGFBP5 and Wnt were determined to be anti-tumorigenic in breast cancer, however, studies in colon cancer report opposing results." (PMID 36465383, 2022). "For example, MCF-7 breast cancer cells treated with CAF conditioned media had decreased expression of IGFBP5 that was exacerbated by treatment with fulvestrant, another anti-estrogen therapy." (PMID 36465383, 2022). "A tissue microarray analysis of breast carcinomas revealed cytoplasmic staining for IGFBP5 was elevated in samples from patients with invasive carcinomas relative to normal breast epithelium or benign breast tissue." (PMID 36465383, 2022).
breast cancer (continued). "Other BPs such as IGFBP-1, IGFBP-2, and IGFBP-5 also play a role in breast cancer, but were outside the scope of this study." (PMID 33767994, 2021). "Another gene overlapping the GWAS for thyroid-stimulating hormone and breast cancer is IGFBP5, indicating the shared growth hormone/insulin-like growth factor (GH/IGF) pathways between thyroid function and breast cancer." (PMID 32838791, 2020). "In MCF-7 breast cancer cells, IGFBP-5 promoted cell survival and adhesion via an IGF-independent mechanism." (PMID 32194505, 2020). "IGFBP5 plays as a tumor suppressor in breast cancer through estradiol-triggered activation of the Akt/PKB pathway." (PMID 33282953, 2020). "IGFBP-5 interacted directly with alpha2beta1 integrin on human breast cancer cells in vitro and promoted survival and adhesion but inhibited migration." (PMID 32194505, 2020). "IGFBP5 is a tumor-suppressor gene for leukemia, osteosarcoma, breast cancer, and pancreatic cancer and participates in cell biological functions, such as cell metastasis and apoptosis." (PMID 33490103, 2020). "Aside from its cytokine binding function, IGFBP5 protein overexpression was shown to suppress cell growth in human melanoma, osteosarcoma, and breast cancer cell lines emphasizing its function in regulating cell proliferation." (PMID 32698886, 2020). "Some studies have also reported a positive correlation between overexpression of IGFBP5 and the presence of ER in breast cancer cell lines." (PMID 31605532, 2020). "A previous study has shown that this gene is down-regulated downstream of IGFBP5, silenced in response to stromal cells in ER α-positive breast cancer cells." (PMID 31238876, 2019). "IGFBP5 induced apoptosis and cell cycle arrest in breast cancer cells; and it inhibited the tumorigenicity of head and neck squamous cell carcinoma in vivo and in vitro." (PMID 30745575, 2019). "IGFBP5 expression is altered in various cancers, including breast cancer, neuroblastoma, osteosarcoma, lung cancer, colon cancer, and its impact on prognosis has been shown to be cell type-dependent and tissue type-dependent." (PMID 28882129, 2017). "Collectively, these results show a strong correlation between history of pregnancy and breast cancers that are characterized by a PAPP‐A/TACS‐3/IGFBP‐5 signature." (PMID 26951623, 2016). "Our data indicate that the formation of spontaneous mammary tumors in PAPP‐A transgenic mice is driven by the proteolytic degradation of IGFBP‐5 during involution." (PMID 26951623, 2016). "Further studies with a large sample size and functional experiments are needed to clarify importance of tumoral IGFBP5 expression and its molecular function in breast cancer metastasis." (PMID 26569312, 2015). "Our group previously reported that apoptotic and migratory potential of IGFBP5 depends on cellular localization which is regulated by nuclear localization signal into C-terminal domain of the protein in breast cancer cells." (PMID 26569312, 2015). "In this study, thirty-eight breast cancer and adjacent normal breast tissue samples were used to determine IGFBP5 expression by qPCR." (PMID 26569312, 2015). "In breast cancer patients, high serum levels of IGFBP-5 correlated with improved time to treatment failure of cixutumumab." (PMID 26217584, 2015). "In the context of breast cancer, IGFBP-3 and IGFBP-5, secreted by carcinoma-associated fibroblasts (CAFs), inhibit detachment-induced cell death, known as anoikis, via regulation of ERK-MAPK activation." (PMID 26217584, 2015). "Further studies with a large sample size are needed to clarify tumoral expression of IGFBP5 and its clinical significance in breast cancer." (PMID 26569312, 2015). "IGFBP-5 induced breast cancer cell MCF-7 adhesion and inhibited its migration in an IGF-independent manner." (PMID 26103640, 2015). "Our previously published paper has shown the role of IGFBP5 on metastatic capacity of breast cancer." (PMID 26569312, 2015).